VDR (vitamin D receptor)
Diseases named in the same sentence as VDR in open-access papers (continued):
Sharing a sentence is not in itself a finding about the gene and the disease.
infectious disease (26 papers, 2012 to 2024). A disorder directly resulting from the presence and activity of a microbial, viral, or parasitic agent in humans. "A growing body of evidence suggests an association between VDR polymorphisms and susceptibility to diverse infectious diseases." (PMID 38702336, 2024). "In conclusion, the majority of the studies reported here agree that VDR hypermethylation is a hallmark of increased susceptibility to infectious diseases." (PMID 38203278, 2023). "Several host genes are associated with numerous infectious diseases, one of them being the vitamin D receptor (VDR)." (PMID 38099246, 2023). "In summary, a lot of studies have been conducted through the years to understand the role of Vitamin D Receptor polymorphism in susceptibility to infectious diseases." (PMID 26693353, 2015). "Previous studies have demonstrated that specific VDR SNPs are associated with vitamin D-related disease conditions and susceptibility to infectious diseases." (PMID 26294193, 2015). "Similarly, 4 VDR SNPs at restriction enzyme sites, Fok1, Bsm1, Apa1, and Taqα1, have been associated with vitamin D-related disease conditions and susceptibility to infectious diseases." (PMID 26294193, 2015). "VDR is known to exhibit large polymorphism, which might contribute to different infectious disease." (PMID 24587317, 2014). "Our current study reveals that VDR plays a crucial role in facilitating Ca2+ absorption in porcine kidney epithelial PK-15 cells during PRV infection, thereby broadening our understanding of VDR’s significance in the context of infectious diseases." (PMID 39475231, 2024). "Among infectious diseases, recent data on the role of VDR epigenetic mechanisms in HIV disease are also emerging." (PMID 38203278, 2023). "In addition, a change in the carrier of the FokI polymorphic variant leads to the formation of a short form of the VDR protein, which leads to higher transcriptional activity and increased cytokine expression, and may be associated with autoimmune and infectious diseases." (PMID 33330279, 2020). "Vitamin D derivatives and their receptor (VDR) are potent modulators of immune responses in various diseases including malignancies as well as in metabolic and infectious disorders." (PMID 31864292, 2019). "VDBP and VDR polymorphisms, and low winter 25-OHD3 serum concentrations may be risk factors for infectious diseases and chronic conditions related to the dysregulation of the vitamin D pathway." (PMID 23185470, 2012). "In contrast to the previous four VDR genetic variations, the number of studies focusing on the potential relationship between this SNV site and the development of infectious disorders remains limited." (PMID 35242885, 2022).
neurological diseases (17 papers, 2013 to 2025). "Association between SNVs in the VDR and GC vitamin D‐binding protein genes and the risk for other neurological diseases has been a matter of several studies." (PMID 37553799, 2023). "The rationale behind this project was that genetic studies on vitamin D receptor polymorphisms had indicated its involvement in neurological disorders like PD." (PMID 32908795, 2020). "In nervous system diseases the role of VDR polymorphism is interesting because VDR is widely expressed in the human brain." (PMID 23984350, 2013). "Additionally, the functional consequences of numerous VDR mutations remain poorly characterized, especially in the context of neurological diseases, making it difficult to predict individual responses to VitD-based therapies." (PMID 41441206, 2025). "However, recent results on the association between VDR gene polymorphisms and different neurological diseases are somewhat contradictory, and the role of VDR in the aetiology of neurological diseases is still uncertain." (PMID 29160835, 2017). "Several lines of evidence propose contribution of VDR signaling in the neurodevelopment and pathology of neurologic disorders." (PMID 35279108, 2022). "VDR expression has also been studied in other neurological diseases." (PMID 33833274, 2021). "Recent research also implicates the vitamin D receptor (VDR) in the regulation of folate transport across the BBB, especially in certain neurological diseases." (PMID 41010482, 2025).
immune diseases (15 papers, 2012 to 2026). "The effectiveness of vitamin D depends on its receptor (VDR), and variations in the VDR gene, particularly SNPs, have been linked to immune dysfunctions." (PMID 40584095, 2025). "Single nucleotide polymorphisms (SNPs) in the VDR gene affect protein responsiveness and have been associated with numerous immune dysfunctions." (PMID 36829806, 2023). "VDR gene polymorphisms are important factors for normal enamel development and have been shown to contribute to susceptibility to various immune diseases." (PMID 29259981, 2017). "Some studies have shown a relationship between VDR polymorphisms and bone mineral density, serum 25(OH)D levels, and neoplastic and immune diseases." (PMID 26161090, 2015). "Polymorphisms of VDR and vitamin D3 (VitD3) serum levels have been correlated to (auto)immune-diseases development since VDR is expressed in several immune cell types." (PMID 36432658, 2022). "So, these variations may influence the biological function of VDR/VEGF/IL-18/MBL, result in immune dysfunction, cause chronic inflammatory hepatocellular injury, and ultimately confer susceptibility to HCC." (PMID 31830994, 2019). "A recent study found that numerous SNPs correlated with immune disorders represent binding sites for VDR and NF-κΒ, and suggests that VDR may regulate transcription indirectly through its interaction with NF-κB." (PMID 30828578, 2018). "Both VDR−/− and CYP27B1−/− mice have serious developmental problems that lead to dermatological, skeletal, reproductive and immune dysfunction." (PMID 23049920, 2012).
adenocarcinoma (14 papers, 2006 to 2025). A common cancer characterized by the presence of malignant glandular cells. "In this study, we demonstrate that its precursor, 25(OH)D3, decreased cell count and viability, induced apoptotic cell death, and upregulated the gene and protein expression of VDMS enzymes (CYP27B1 and CYP24A1) and receptor (VDR) in the HeLa adenocarcinoma cell line." (PMID 40362248, 2025). "One study reported no VDR staining in normal oesophageal squamous mucosa, whereas Barrett's mucosa and low grade dysplasia had strongly positive VDR staining (95% and 100%, respectively), which then decreased slightly in tissue from patients with adenocarcinoma (79%)." (PMID 30344947, 2018). "Furthermore, four out of the 15 NRs—ERRα and VDR with reduced expression and Coup-TFα and β with increased expression- showed an adenocarcinoma specific expression pattern." (PMID 26244663, 2015).
neurodegenerative disease (14 papers, 2015 to 2026). A disorder of the central nervous system characterized by gradual and progressive loss of neural tissue and neurologic function. "The contribution of VDR gene polymorphisms to susceptibility to neurodegenerative diseases and conditions associated with calcium metabolism has been frequently reported in the literature." (PMID 34936251, 2021). "Our data indicate that VPA may modulate the differential expression of proteins involved in mitochondrial function and vitamin D receptor-mediated chromatin transcriptional regulation and proteins implicated in the pathogenesis of neurodegenerative diseases." (PMID 32806546, 2020). "Other genes’ polymorphism associated with increasing the risk of AD include vitamin D receptor (VDR) gene polymorphism, which affects the affinity of vitamin D to its receptor and may cause neurodegenerative diseases and neuronal damage." (PMID 33302541, 2020). "A single-nucleotide polymorphism in the VDR gene can influence the affinity of vitamin D to its receptor and thus may be related to neurodegenerative diseases and neuronal damage by altering vitamin D-mediated pathways." (PMID 26259787, 2015). "The VDR is expressed in diverse brain regions and has been implicated in the neuroprotective, antiaging, prosurvival, and anti-inflammatory action of vitamin D. Accordingly, a relationship between vitamin D insufficiency and susceptibility to neurodegenerative diseases has been suggested." (PMID 36831327, 2023). "In line with the concept of the neurovascular unit in pathomechanisms of neurodegenerative diseases, a discussion of the role of the VDR in regulating the immune and vascular brain systems is also included." (PMID 36831327, 2023). "It has been emphasized that vitamin D and VDR levels may be environmental and genetically influential factors in the etiopathogenesis of various neurodegenerative diseases such as MS, PD, AD, and ALS." (PMID 40464816, 2025). "The bioactive form of vitamin D is vitamin D3 (VitD3, also known as calcitriol), which exhibit antioxidant and neuroprotective properties through binding with the vitamin D receptor (VDR), potentially useful against neurodegenerative disease." (PMID 39328008, 2024).
bacterial infection (11 papers, 2010 to 2025). "Consistently, global deletion of vitamin D receptor (VDR) or deficiency in VDR ligand in mice leads to reduced colonic ILC3s and impaired ILC3 response, leading to increased susceptibility to bacterial infection compared with wild-type mice." (PMID 33193381, 2020). "In contrast, another study reported that VDR knockout (KO) mice had enhanced resistance to bacterial infection due to increased frequencies of ILC3s in the gut and enhanced expression of IL-22 as well as anti-bacterial peptides." (PMID 33193381, 2020). "Uropathogenic E. coli induced increased VDR levels and caused nuclear translocation in mouse and human bladder cells independently of vitamin D, while vitamin D was necessary for VDR transcriptional activity upon bacterial infection." (PMID 28749951, 2017). "Cathelicidin was identified several years ago as a target for transcriptional regulation by 1,25(OH)2D3-liganded vitamin D receptor (VDR) and has a critical influence on the innate immune defense against invasive bacterial infection." (PMID 23614044, 2013). "VDR activation suppresses hepatic Il6 expression and plasma IL-6 levels increased by BDL, and bacterial infection increases serum IL-6 levels to a greater extent in VDR-null mice." (PMID 23240054, 2012). "Thus, we speculated that the VDR-Bmi1 signaling pathway of active vitamin D may also play a role during bacterial infection." (PMID 35957979, 2022). "In addition, vitamin D may protect the vagina from bacterial infection by increasing the stability, proliferation and differentiation of stratified squamous epithelial cells through activation of the VDR, p-RhoA and p-Ezrin pathways, as suggested in other systems." (PMID 40469676, 2025).
bone disorder (10 papers, 2006 to 2024). "In humans, mutations in the VDR gene lead to impaired vitamin D synthesis, resulting in systemic and bone disorders, as well as hair thinning and hair loss, which is consistent with our findings." (PMID 38792630, 2024). "Numerous studies investigated the association between VDR variants (ApaI and TaqI) and bone disorders and disparate results were detected." (PMID 34351532, 2021). "Extensive studies focused on this VDR gene in various phenotypes have revealed the association between VDR polymorphism and many non-skeletal diseases." (PMID 16507161, 2006). "At the molecular level, AFB1 at levels as low as 75 ppb impaired bone homeostasis via disruption of the vitamin D receptor and calcium and phosphorus transporters, potentially contributing to lameness and other bone disorders in broilers." (PMID 38393156, 2024). "Functional studies and exploration of gene-environment interactions may pave the way for personalized treatment strategies tailored to individual VDR genotype, optimizing the management of mineral and bone disorders in CKD and ESRD." (PMID 39156357, 2024). "Moreover, the development of innovative therapeutic strategies targeting the VDR or its downstream signaling pathways holds promise in enhancing the management of mineral and bone disorders in this patient population." (PMID 39156357, 2024). "Moreover, elucidating the molecular mechanisms underlying these associations could pave the way for developing novel targeted therapies that are aimed at modulating VDR activity and mitigating mineral and bone disorders in CKD patients." (PMID 39156357, 2024). "Worth noting however, is we did not observe very highly significant (P < 0.001) association of VDR and LRP5 with body conformation, FL soundness traits and overall leg action, even though these two had been considered as important candidate genes for human bone disorders." (PMID 19284518, 2009).
genetic disease (10 papers, 2008 to 2025). "Vitamin D-dependent osteomalacia is a genetic disease induced by mutations in 25-(OH) vitamin D-1α-hydroxylase (type 1) or vitamin D receptor (type 2)." (PMID 35029240, 2022). "Vitamin D-dependent rickets types 1 and 2 are autosomal recessive genetic diseases due to mutations in the renal 1-hydroxylase (CYP27B1) and vitamin D receptor (VDR) genes, respectively." (PMID 35163424, 2022). "In addition to allelic variations of the VDR gene, a rare genetic disorder has been described in which the VDR gene contain mutations that renders the gene product non-functional." (PMID 23785369, 2013).
cardiac disease (7 papers, 2015 to 2025). "Another study in a Caucasian population (from Egypt) (50 cases/50 controls) also reported an association between the VDR FokI polymorphism and the presence of congenital heart disease defects." (PMID 35955825, 2022). "Although the mechanisms underlying the role of vitamin D in heart disease remain unclear, their relationship is possible due to the presence of vitamin D receptors (VDR) in vascular smooth muscle cells." (PMID 41536823, 2025). "Vitamin D/vitamin D receptor (VD/VDR) deficiency is involved in the pathogenesis of various cardiac diseases; however, the exact underlying mechanism remains unclear." (PMID 33981701, 2021). "In heart disease, VD can bind to the VD receptor (VDR) in the heart to regulate the activity of NR4A1 and play a protective role." (PMID 40823027, 2025). "Our RNA sequencing revealed an overall upregulation of the VDR/RXR activation pathway which may provide further insights into the role this pathway plays in cardiac disease." (PMID 32189431, 2020). "Growing evidence of vitamin D's anti-fibrotic actions may indicate supplementation efforts in the setting of HF, or lead to the development of novel non-calcemic VDR agonists to target VDR signaling for treatment of pathological fibrosis in cardiac disease." (PMID 26061181, 2015).
colorectal (7 papers, 2012 to 2025). "Meanwhile, VDR deficiency can deteriorate liver IR injury by disturbing M2 macrophage polarization." (PMID 37529163, 2023). "Nevertheless, there is little clarity on the mechanism of VDR in the process of liver IR injury." (PMID 37529163, 2023). "Hence, we assumed that M1/M2 macrophages took part in liver IR injury and VDR mediated liver IR injury through influencing M1/M2 macrophage polarization." (PMID 37529163, 2023).
musculoskeletal diseases (7 papers, 2021 to 2025). "In this scenario, previous studies have underlined the potential role of VDR polymorphisms in musculoskeletal disorders." (PMID 36362456, 2022). "Given the importance of the VDR in mediating the actions of vitamin D, its study represents an important goal in the understanding of musculoskeletal disorders pathogenesis, especially OP disease." (PMID 36980815, 2023).
hematological malignancies (6 papers, 2010 to 2024). "Many studies have been carried out to determine whether there are genetic variations in a specific region of the vitamin D receptor (VDR) linked to hematological malignancies." (PMID 38125732, 2024). "Vit-D receptor (VDR) agonists can inhibit proliferation, induce differentiation, aggravate apoptosis and decrease pro-inflammatory cytokines production in hematologic malignancies and also have a synergistic effect with some chemotherapeutic drugs." (PMID 36420327, 2022). "Ultimately, the ubiquity of the vitamin D receptor and the myriad physiologic effects that have been found suggest multiple mechanisms of potential benefit from the use of Vitamin D in the treatment of hematologic disease." (PMID 23778150, 2013). "Lack of VDR or APC inactivation can induce haematological disorders." (PMID 27768599, 2016).
intestinal diseases (6 papers, 2011 to 2026). "Although there are studies focused on the impact of genetic polymorphisms in VDR and vitamin D supplementation on intestinal diseases, they remain largely inconclusive at this time." (PMID 42232580, 2026).
digestive system tumours (5 papers, 2016 to 2023). "The present meta-analysis, which pooled these disparate results, preliminarily showed that VDR expression is associated with overall survival in digestive system tumours." (PMID 37561808, 2023). "The correlation between VDR expression and OS of digestive system tumours was investigated in eight studies involving 3,109 patients." (PMID 37561808, 2023). "On the other hand, evaluating the expression level of VDR is beneficial for formulating appropriate treatment plans for patients with digestive system tumours." (PMID 37561808, 2023). "We demonstrate that in general, VDR expression is a prognostic indicator for digestive system tumours." (PMID 37561808, 2023). "Published studies (as of Mar 30, 2023) assessing the prognostic role of VDR in digestive system tumours were retrieved." (PMID 37561808, 2023). "Detection of VDR expression not only helps to evaluate prognosis but also to formulate more precise treatment plans for patients with digestive system tumours." (PMID 37561808, 2023). "The prognostic value of vitamin D receptor (VDR) in a variety of digestive system tumours remains controversial." (PMID 37561808, 2023). "This study aimed to meta-analyse published studies on VDR and prognosis to verify the role of VDR in the prognosis of patients with digestive system tumours." (PMID 37561808, 2023). "VDR expression is a prognostic indicator in digestive system tumours and may also be used as a reference for vitamin D supplementation." (PMID 37561808, 2023). "In addition to VDR expression, serum vitamin D levels can be used to evaluate prognosis of patients with digestive system tumours." (PMID 37561808, 2023). "Accordingly, VDR expression is a potential prognostic indicator of digestive system tumours." (PMID 37561808, 2023). "Our meta-analysis is the first to study the prognostic value of VDR in digestive system tumours." (PMID 37561808, 2023). "Therefore, by detecting VDR expression, oncologists can not only better evaluate the prognosis of patients with digestive system tumours but also formulate more precise treatment plans." (PMID 37561808, 2023). "In addition, the biological functions of VDR in different digestive system tumours differ, which may be another more important reason." (PMID 37561808, 2023). "Therefore, we sought to determine the prognostic role of VDR in digestive system tumours." (PMID 37561808, 2023).